TNF (tumor necrosis factor)
Diseases named in the same sentence as TNF in open-access papers (continued):
Sharing a sentence is not in itself a finding about the gene and the disease.
infection (continued). "Given that TNF was also downregulated and exhibited hypermethylation on its promoter region in our data, we assumed that TNF was inhibited by HIV-1 to facilitate its replication during the infection of T cells." (PMID 33013899, 2020). "Under infection, T. gondii triggers IL-12 production, which acts with TNF to induce IFN-γ by natural killer (NK) cells; being that the infection normally triggers protective cell-mediated immunity, in which IFN-γ has a central role." (PMID 32295126, 2020). "As infection persisted, we observed an increase in the cytokine TNFα; a decrease in the cytokine IL-6; an increase in T-cell priming co-receptors CD80/86, and MHCII; and a decrease in CD103 and IL-10." (PMID 32635236, 2020). "In the complete TNF knockout mice, we noticed striking higher infiltration of plasma cells at weeks 1 and 2 post-infection compared with TNFf/f or BTNF-/- mice." (PMID 32742607, 2020). "RSV infections are characterized by the rapid (18–24 h following infection) and transient induction of early innate immune mediators such as type I IFNs, IL-6, and TNF-α." (PMID 33123150, 2020). "The impaired ability of hybrid Th1/Tfh to help antibody production is likely due to an antagonism regulating Tfh effector functions through the network of STAT4 and T-bet expression and the effects of IL-2, IL-12, IFN-γ, and/or TNF, depending on the infection." (PMID 32634740, 2020). "At peak infection, IL‐10 production increased (P = 0.06), with a significant increase in TNF/IL‐10 co‐production in response to pRBC restimulation (P = 0.04)." (PMID 32566226, 2020). "IGF1 decreases in response to pro-inflammatory cytokines, such as tumor necrosis factor-α, interleukin (IL) 1β, and IL-6; low circulating levels of IGF1 are associated with infection, trauma, and aging." (PMID 32692761, 2020). "Although we did not observe a significant increase in γδ T cells after H1N1pdm09 infection, we showed that γδ T cells produce IFNγ and TNF as early as day 2 post infection ex vivo, in agreement with studies in mice." (PMID 33603740, 2020). "Among its numerous actions, it can be cited that TNF-α is a neutrophil and eosinophil chemoattractant; it stimulates the leukocyte accumulation, proliferation, and differentiation at the site of infection and contributes to the induction of oxidative stress." (PMID 33053905, 2020). "Nevertheless, immunosuppressive therapies are often used in combination with biological therapies (especially with anti-TNF drugs) in order to reduce their immunogenicity, raising concerns about possible side effects, especially infections and malignancy." (PMID 32269571, 2020). "Each of the inflammatory genes exhibited unique response, with MCP-1 transcripts up-regulated early in the infection up to 10 days post infection (dpi) and TNF-α transcripts later in the infection at 20 dpi." (PMID 32076422, 2020). "We observed down regulation of IL-22 and IL-10 in spleen of salmon at chalimus stage of infection and an increase in IL-1β, TNF-α and IL-8 at subsequent pre-adult stage in group 2." (PMID 33006991, 2020). "IL-6 KO infected mice produced lower levels of the proinflammatory cytokines IFN-γ and TNF-α, at 1 week and 6 weeks post-infection compared to wild-type infected animals." (PMID 33322581, 2020). "The amount of TNF-α in the intestine followed the same trend, where loops infected with the C. jejuni wild-type strain had increased amounts of TNF-α at 12 hours post-infection when compared to the controls." (PMID 32887530, 2020). "In the case of IFN-γ and TNF-α, only an increase in its expression is observed due to infection in the taiep group (p < 0.01)." (PMID 32817660, 2020). "Pro-inflammatory cytokines, such as interferons, interleukins, and tumor necrosis factor (TNF), are the main regulators of the lung environment during infection." (PMID 32854331, 2020). "At 14 days post infection (directly after treatment) very high concentrations of IL-2, IL-13, IL-10, IFNγ, IL-6, and TNFα were observed." (PMID 32226027, 2020).
infection (continued). "Infection with inflammatory environment can prolong QT interval due to the effect of inflammatory cytokines (interleukin-6, tumor necrosis factor-α, interleukin-1) on potassium and calcium channels." (PMID 32154029, 2020). "Even when a multiplicity of infection (MOI) of 10 was used, the secretion of IL-1β was still low, whereas that of TNF increased, showing that the macrophages were upregulating their response to infection with higher doses of M. tuberculosis 6C4." (PMID 32327653, 2020). "Analysis of the cytokine subsets in the uGT showed that the Th1 effector cytokine subsets expressing TNFα/IFNγ and TNFα/IFNγ/IL-2 were present at day 14 and day 21 post infection." (PMID 31993218, 2020). "It is now well established that the proinflammatory cytokines play several crucial roles in onset of CL, which varies from the resistance or the host immune response to infection, especially tumor necrosis factor alpha (TNF-α) and interferon-gamma (IFN-γ)." (PMID 32404058, 2020). "We found that BMDC infection with LDPm or LDAm attenuated LPS- and TNFα-induced Akt phosphorylation." (PMID 33370418, 2020). "The expression and mean fluorescence intensity (MFI) of MHC II on brain Fo B cells of TNF-/- mice were found to be significantly lower at week 3 post-infection compared with BTNF-/- and TNFf/f mice." (PMID 32742607, 2020). "This study also confirms that surgical patients with infection have suppressed host defences, specifically a decreased capacity for TNF-α production in response to LPS stimulation and decreased HLA-DR expression." (PMID 32699255, 2020). "The levels of IL-1β, IL-6, and TNF-α in serum and lung samples were compared between innate immune effector depleted mice and control mice 24 h after infection." (PMID 33163539, 2020). "It has been well described that during infection with the influenza virus, the expression of TNF-α in lung epithelial cells was higher, exerting powerful anti-influenza virus activity." (PMID 32354030, 2020). "Upon infection, both cytokines (TNFα and IL6) and chemokines (KC and MCP1) levels were significantly increased in Ccn1flox/flox mice, whereas this inflammatory response was greatly reduced in Ccn1ΔMyeloid mice." (PMID 32144270, 2020). "As we expected, the expression and MFI of plasma cell-expressing CD40 and CD86 in BTNF-/- and TNF-/- mice were comparable to those of TNFf/f mice at week 3 after infection." (PMID 32742607, 2020). "During infection inflammatory cytokines such as tumor necrosis factor α (TNF-α), interleukin-1 (IL-1) and/or interleukin-6 (IL-6) are enhanced." (PMID 32854285, 2020). "It has been reported that in the activation of the defense mechanisms, the production of TNF-α, along with IL-1β and IL-6, induces a protective inflammatory response for infection control." (PMID 32423093, 2020). "Activated IFN-ɣ+ T cells, natural killer (NK) cells, tumor necrosis factor (TNF)-α+ monocytes, IL10+ and TNFα+ myeloid dendritic cells, and TNF-α+ plasmacytoid dendritic cells persisted at least until day 30 after infection." (PMID 32289501, 2020). "After 2 h of infection with Mtb WT, there was a significant upregulation of immune modulators such as TNF, IL-1A, IL-1B and IL-6." (PMID 32938685, 2020). "Mice were injected intraperitoneally with an anti-TNF-α monoclonal or a control antibody on days 0, 2, 4, and 6 of infection, with fecal samples taken on days 0, 3, and 7 of infection." (PMID 32071269, 2020). "Tumor necrosis factor (TNF) is a potent pro-inflammatory cytokine with a pivotal signaling role in the host defense against infection and injury, as well as controlling the survival of target cells." (PMID 32948801, 2020). "At 16 h post-infection, a mean of 16.05% ± 2.51% (standard deviation) and 15% ± 1.21% of BMMCs were positive for IL-6 and TNF-α, respectively." (PMID 33261178, 2020).
infection (continued). "We present a worst-case scenario of the infection establishing itself at the time of the maintenance administration of anti-TNF-alpha therapy in a patient on combination immunosuppression with methotrexate." (PMID 32824122, 2020). "The response of TNF-α at the beginning of the infection indicates immunity protection against plasmodium." (PMID 32190083, 2020). "The inflammatory cytokines IL-1β and IL-6 as well as TNFα showed similar trends of increase in both infection protocols, albeit with more prominent increases of TNFα under SARS-CoV-2 infection." (PMID 33163005, 2020). "It has been reported that IL-1β and TNF-α play critical roles in the host defense against infection and are responsible for early inflammatory responses." (PMID 32746898, 2020). "Even inflammation, infection and stress are known to induce the expression of TNF-α and regulate diverse immune functions." (PMID 32120970, 2020). "Gene expression of IFNB1, TNF, and IL-10 was measured 24 h following infection with Mtb H37RV at MOI of one." (PMID 33240287, 2020). "This study did not address lung damage like those in mice, but it is possible that although TNF-α induces lung damage during infection, it is necessary for a fully functional host response." (PMID 32974217, 2020). "Several studies have shown that infection of BECs with Aspergillus fumigatus leads to the release of pro-inflammatory cytokines, mostly IL-6, IL-8, or tumor necrosis factor-α provided that the infection time is more than 6 h and allows conidia germination." (PMID 32528481, 2020). "For example, one study showed that plasma levels of IL-2, IL-6, IL-8, IL-10, and TNF-α, were found to be higher in patients with severe infection than those with mild to moderate infection." (PMID 32984253, 2020). "In the present study, we found that the expression of antiviral genes (e.g., PKR, OAS1, and Mx2) and inflammatory cytokines (e.g., IFN-α and TNF-α) were significantly reduced within 0–4 h post-infection." (PMID 32133381, 2020). "Previous meta-analyses of randomized controlled trials reported that infection risks increased after the use of TNF-α inhibitors in RA patients." (PMID 33021982, 2020). "Contrastingly, at later stages of infection, TNF-α induces necrosis of infected cells in the granuloma core leading to bacterial leakage and replication, making direct TNF-α cytokine therapy unsuitable for ROS and iNOS induction." (PMID 32849525, 2020). "In contrast, strikingly reduced IgA, IgG, and IgM levels were found at week 3 after infection in mice with complete TNF ablation when compared with TNFf/f and BTNF-/- mice." (PMID 32742607, 2020). "Either IAL alone or in combination with penicillinG resulted in a significant decrease in TNF-α, IL-1β and IL-6 levels in the fluid at 36 h post infection." (PMID 32110983, 2020). "IFNα, IFNβ, IFNλ1, Rig-I, IRF3, IRF7, OAS-1, MxA, IL6, IL8, and TNFα expressions were increased at either day 1 or day 2 in HFDPCs post-infection or on both days." (PMID 32121148, 2020). "Infection of P. zopfii GT-II in macrophages upregulated mRNA expression of IL-1β, TNF-α and Cxcl-1 (2 h)." (PMID 31959834, 2020). "Consistent with this, a knockout of MyD88 in THP-1 cells completely abolished the expression of the inflammatory cytokines TNF-α and IL-1β upon infection with C. acnes, L.m., or LPS." (PMID 33178195, 2020). "ELISA results revealed that M. bovis infection induced the secretion of IL-1β, IL-10, and TNF-α after 24 h of infection in THP-1 cells." (PMID 32265874, 2020). "It was suggested that low levels of TNF-α, IL-2, IL-4, and IL-13 during early infection were predictive markers of chronic joint pain." (PMID 32471152, 2020). "The high potency of TNFα in terms of protecting the host from infection requires stringent control of this cytokine expression." (PMID 33057437, 2020).
infection (continued). "This cell population increases both at the systemic level and at the site of infection; apparently its presence is regulated by a TNF-dependent pathway, carrying out phagocytosis processes, and they are an important source of pro-inflammatory cytokines." (PMID 33266385, 2020). "Our assessment of MCMV-infected myeloid or non-myeloid cells reinforces evidence that vICA suppression of CASP8 activation and apoptosis acts against TNF-dependent signaling during infection." (PMID 33126536, 2020). "Ms_YrbE3A infection resulted in the highest concentrations of pro-inflammatory cytokines, including TNF-α, IL-1β, IL-6, MCP-1, IL-1α, IL-12p70, and IFN-γ, in the lungs at 2 d PI and later decreasing rapidly from 4 to 21 d PI." (PMID 32316659, 2020). "Owing to its ability to recruit and activate immune cells, TNF-α is decisive for early inflammatory responses that help in clearing infection." (PMID 32545606, 2020). "TNF contributes to protection against infection in an experimental model and acts as co-stimulator for the crucial production of IFN-γ." (PMID 32760383, 2020). "IFN-γ, like TNF, play an important role in the resistance to infection of T. gondii due to the ability of macrophage activation." (PMID 31947510, 2020). "Intriguingly, the ΔCagPAI mutant was able to induce expression of IL-6 but failed to induce expression of TNFα after 1 h of infection, whereas Brefeldin A treatment resulted in decreased IL-6 but stable TNFα mRNA levels upon infection with the wt strain." (PMID 33023610, 2020). "Human RA patients that were treated with anti-TNF biologicals had an increased general infection rate." (PMID 32760383, 2020). "Inflammatory markers, such as C-reactive protein (CRP), interleukin-6 (IL-6), and tumor necrosis factor-α (TNF- α) are shown to markedly increase in response to infection and tissue damage, as well as in active state of disease." (PMID 32731638, 2020). "IL-1β is a potent pro-inflammatory cytokine that together with TNF-α plays a crucial role in host-defense responses to infection by bacteria, virus, parasites." (PMID 32983178, 2020). "Our results show that beside the direct effect of S. aureus leading to the cleavage of extracellular SP-A, there is an indirect effect based on infection via the cytokine production, notably by TNF-α." (PMID 32316261, 2020). "Two days after infection (day 2), the levels of pro-inflammatory cytokines IL-6, TNF-α, and IL-1β were significantly higher in the group ZE compared with the group ST." (PMID 32486242, 2020). "In this study, infection of the tilapia meninges by Sta induced the production of TNF-α by phagocytes, initiating the neuroinflammatory process in the brain tissue." (PMID 33233716, 2020). "We found that BMDC infection with LDPm for 24 h also inhibited the CD40 upregulation induced by TNFα." (PMID 33370418, 2020). "Heightened concentrations of IL-6, TNFα, and IL-4 support previous pathogen exposure and a possibility of current infection." (PMID 32849592, 2020). "Addition of LL-37 to the mammary epithelium stimulated transcriptional expression of IL-1β and TNF-α at a later point (8 h post-infection) (p < 0.05)." (PMID 32117805, 2020). "IL-1β and TNFα expression levels can be used to better understand the host response to infection and expression of IL-1β and TNFα in response to various infections has been reported previously in tilapia." (PMID 31554184, 2019). "Macrophage activation and production of pro-inflammatory mediators, such as TNF-α, have been well demonstrated to play a critical role for parasite control during the acute phase of infection." (PMID 31244833, 2019). "H99-α-infected mice significantly skewed the Th cytokine balance in a way that suggests more protective Th1 polarization, indicating a protective role of the TNF-α-producing transgenic C. neoformans strain in the efferent phase of infection." (PMID 31404168, 2019).
infection (continued). "A study comparing L. major—promastigotes and amastigotes infection of macrophages—showed that while infection with promastigotes induced inflammatory mediators, such as TNF-α and chemokines, amastigote infection was silent resulting in increased parasite load." (PMID 31608245, 2019). "The blood of the mice infected with Δ1717 contained lower concentrations of IL-1β, MCP-1, and TNF-α at 6, 9, and 12 h post-infection." (PMID 31684161, 2019). "Comparing the mean intensity values (MFI) of memCD95L reflected the specific effect of TNF, since addition of etanercept reduced the concentration of memCD95L on both PBMO and CBMO after TNF treatment and infection, respectively." (PMID 30897723, 2019). "In the current study, lung GM-CSF, TNF- α cytokines remain suppressed, while 1L-12/p40 is significantly increased 24 h post infection and 48 h after alcohol was initially administered (24 h prior to infection)." (PMID 31821337, 2019). "Bio-Plex assays were utilized to measure cytokine secretion of IFN-α, interleukin- (IL-) 6, IFN-γ, and TNF-α following infection with LCMV or stimulation with polyI:C." (PMID 30882005, 2019). "The levels of the pro-inflammatory cytokine TNF-α in the mice colon increased significantly in response to infection, but were significantly reduced by pretreatment with both ZS2058 and LGG." (PMID 30842764, 2019). "During the course of an infection, the excessive circulating ranges of TNF-α, IL-1β, and IL-6 indicate a rapid array of host responses, such as fever and leukocyte chemotaxis." (PMID 30949497, 2019). "Other cytokines such as G-CSF, IL-6, and TNF-α were apparently increased by FCPLJ treatment especially on day 3 post infection." (PMID 30744623, 2019). "Together this indicates a possible protective effect of the Kcc1M935K/M935K mice against ECM by altering the balance of IFN-γ and TNFα responses to infection." (PMID 31015511, 2019). "In comparison, TNFα expression was significantly upregulated at day 1, 2, and 3 post-infection but only at 0.1 μM of PACAP, the highest concentration of the AMP." (PMID 31105711, 2019). "Such pathways are activated either by mono- or polymicrobial infections, resulting in an increase in the expression of proinflammatory molecules such as IL-6, IL-8, IL-1β, and TNF-α." (PMID 31049022, 2019). "Cytokines like IFN-γ and TNF-α, produced by effector T cells, contribute to control of the infection at chronic stages." (PMID 30642899, 2019). "In contrast, in LysB-treated mice, significant levels of TNF (P<0.01) were detectable at day 16 post-infection (day 6 post-treatment)." (PMID 31425525, 2019). "At the later time point, the infection had minimal if any effect on TNF-α and IL-1β expression in STAT-1-/- and control mice." (PMID 30650607, 2019). "When compared with WT, this reduction is by more than 70–80% for the mutants E90Q and T88G at 24 h post-infection or later, Moreover, the E90Q mutant had a greater ability to reduce the production of TNF-α." (PMID 31561412, 2019). "Conversely, TNF-α and IL-12/p40 concentrations were suppressed ~ 2-fold in mice administered alcohol 3 h prior to infection compared to mice administered alcohol 0.5 h prior to infection." (PMID 31821337, 2019). "Particularly, it was demonstrated that said exosomes can lead to protection against infection by M. tuberculosis in mice through production of iNOS and TNF-α by naive macrophages; a pro-inflammatory response." (PMID 31032233, 2019). "TNF-α also acts on platelet adhesiveness, favoring the formation of thrombus and occlusion of blood vessels and, therefore, reducing infection but also the tissue necrosis." (PMID 31151285, 2019). "In the CD4+ T cell-depleted group, production of IL-2 and IL-10 were decreased in the early stage of infection, and production of IL-17 and TNF-α was decreased in both the early and late stages." (PMID 31608052, 2019).